AGRN (agrin)
Diseases named in the same sentence as AGRN in open-access papers (continued):
Sharing a sentence is not in itself a finding about the gene and the disease.
tumor (continued). "Agrin is frequently overexpressed and secreted in HCC and plays prominent roles in the liver tumor microenvironment (TME) to promote hepatocarcinogenesis and in the tumor mimicking wound healing and repair." (PMID 39123447, 2024). "Besides, we compared the expression of DRGGs between HCC tissues and normal samples and found that most genes, such as AGRN, B3GNT3 and FLNA, were highly expressed in tumor tissues, resulting in a worse patient prognosis." (PMID 37680641, 2023). "Only P4HA1, PMM2, and AGRN exhibited significant correlation with overall survival (OS), and the transcriptomic expression of P4HA1, PMM2, and AGRN was significantly upregulated in tumor tissues." (PMID 37428395, 2023). "AGRN-positive CSCs EVs enhance the activation of YAP through LRP4, promoting tumor growth." (PMID 36358747, 2022). "In published studies, AGRN, ITGAV, FLNC, ILK, and RSU1 were overexpressed in HCC tumor tissues, thereby promoting tumor development, metastasis, and even leading to poor prognosis, which is consistent with our findings." (PMID 36110210, 2022). "The amount of CD31+CD45− ECs within the metastasized tumor was also not significantly reduced following ablation of agrin in pulmonary blood vessels." (PMID 35174224, 2021). "Additionally, function-blocking antibodies that prevent agrin’s interaction with its receptor repertoire similarly inhibited YAP activity in vitro and in vivo and reduced tumor cell growth." (PMID 29415512, 2018). "Importantly, overexpression of Lrp4 and MuSK in HCC tumours (8 out of 11 HCC patients) is consistent with the notion that Agrin functions through the Lrp4–MuSK complex to activate FAK in driving the oncogenic programme of HCC cells." (PMID 25630468, 2015). "Therefore, the LYZ, LCN2, CEACAM5, and AGRN genes, with specific expression along the malignant continuum, may serve as markers for CRC precancerous diagnosis and tumor progression detection." (PMID 39456726, 2024). "Indeed, agrin is detected in both macro- and microvascular ECs, but the role of endothelial agrin in tumor angiogenesis has not been investigated." (PMID 35174224, 2021). "We conclude that there are two different influences on the expression and distribution of AQP4 and -1: firstly the influence of the ECM around the vessels within SEs showing no agrin and dystroglycan expression and therefore no OAPs in the tumor cell membranes." (PMID 26115524, 2015). "Targeting the endothelial derived agrin might not be effective in inhibiting tumor angiogenesis." (PMID 35174224, 2021). "In contrast, the combination therapy showed little effect on the tumor volume of PDX#18 as these tumors had low EGFR–YAP as drug targets, which did not impact agrin." (PMID 40165020, 2025).
cancer (42 papers, 2010 to 2025). A tumor composed of atypical neoplastic, often pleomorphic cells that invade other tissues. "There is mounting evidence that a wide range of glycans, including proteoglycans like syndecans, agrin, serglycin, SLRPs and others, hyaluronan, sialylated proteins, and O-linked glycans, are involved in cancer cell mechanotransduction." (PMID 36693448, 2023). "Beyond these roles, AGRN has been implicated in numerous human cancers." (PMID 40299352, 2025). "Moreover, certain factors, such as performance status, smoking history, and elevated AFP levels, were strongly associated with higher agrin levels among cancer patients." (PMID 39123447, 2024). "We analyzed the relationship between AGRN expression and clinicopathological features in a variety of cancers and found significant associations between AGRN expression in COAD, HNSC, KIRC, LIHC, PAAD, and TGCT at different pathological stages in the TCGA database." (PMID 37841281, 2023). "In addition, we modulated the expression of agrin in aberrant keratinocytes and evaluated processes and characteristics associated with cancer progression in vitro and in vivo." (PMID 29872149, 2018). "Agrin expression confers substrate stiffness‐dependent oncogenic attributes to EGFR‐reliant cancer cells." (PMID 40165020, 2025). "Third, the broader applicability of the agrin‐EGFR‐YAP/TAZ axis in other cancer types, particularly those with high EGFR expression or activation, warrants exploration." (PMID 40165020, 2025). "AS events involving AGRN are present in four out of sixteen adult cancers: ESCA, KICH, READ, and THCA." (PMID 39595158, 2024). "For instance, increased expression of COL6A1, SDC4, FRAS1, AGRN, and COL4A2 has been observed in different cancer types and reported to be associated with metastasis and poor outcomes in patients." (PMID 37987316, 2023). "Combining the results of immune infiltration analysis and ROC analysis, we conducted a pan-cancer analysis of AGRN." (PMID 37841281, 2023). "Since degradation and remodeling of the extracellular matrix are essential processes for cancer cell invasion and involve degradation of agrin, it is conceivable that AQP4 localization and expression is consequently affected." (PMID 35187599, 2022). "Proteoglycan 4 was reported to inhibit carcinoma neovascularization, while glypican-3 and agrin increase the proliferation and angiogenesis of HCC cells." (PMID 36555545, 2022). "Particularly, the heparan sulfate proteoglycan (HSPG) AGRN is a critical regulator for the progression of several cancers, particularly through its involvement in cancer cell migration and shedding." (PMID 31630475, 2020). "Agrin produced by cancer cells, binds to and stabilizes its receptors β1-integrin and Lrp4 on the surface of the vascular endothelial cells." (PMID 33330449, 2020). "Mounting evidence points to another secreted proteoglycan – agrin as a modulator of mechanosignaling in cancer." (PMID 33330449, 2020). "The YAP cytoplasmic sequestration and degradation antagonized by agrin account likely for increased YAP stability in cancer cells having agrin overexpression." (PMID 29415512, 2018). "Irrespectively, these recent findings evoke new insights on the role of secreted agrin in sustaining the nuclear levels of YAP under mechanically stressed conditions such as in cancer, nerve impulse propagation, and organ development and regeneration." (PMID 29415512, 2018). "More importantly, blocking integrin activation also inhibited agrin-YAP induced cancer cell contractility and collagen remodeling abilities." (PMID 29415512, 2018). "Agrin sustained the mechanoresponsiveness of YAP by utilizing FAK phosphorylation in a stiffness sensed manner that correlated with three-dimensional (3D) cancer cell growth." (PMID 29415512, 2018).
cancer (continued). "Here, we highlight the recent perspectives on the role of agrin in mechanosignaling from the ECM via antagonizing the Hippo pathway to activate YAP/TAZ in the contexts of cancer, neuromuscular junctions, and cardiac regeneration." (PMID 29415512, 2018). "On this basis we defined and consequently confirmed novel biomarker candidates such as the extreme C-terminus of the extracellular matrix protein agrin within the set of cancer-enriched immunorectivities." (PMID 20184735, 2010). "Utilizing the Cancer Dependency Map (DepMap), we first analyzed whether the loss of EGFR (via CRISPR Public 22Q4 datasets) in over 1000 cancer cell lines requires agrin as a co‐dependent gene for regulation of cellular proliferation." (PMID 40165020, 2025). "In pan-cancer analysis, the expression levels of AGRN vary in different kinds of tumors and may become an independent prognostic factor for certain tumors." (PMID 37841281, 2023). "Notably, 40 DERIs were found to be specifically detected in the nuclear fraction, and many of these were from known cancer‐related genes, including AGRN, DKC1, PKMYT1, PLK1, and MARS1." (PMID 36461702, 2023). "The analysis showed that various types of cancer expressed AGRN, with the highest level in MESO." (PMID 37841281, 2023). "After further gene expression validation, we finally selected AGRN for pan-cancer analysis." (PMID 37841281, 2023). "Overall, our findings suggest that AGRN may play a part in promoting tumorigenesis and act as a potential cancer prognosis biomarker." (PMID 37841281, 2023). "Overall, this suggests that AGRN holds promising prospects for cancer diagnosis." (PMID 37841281, 2023). "In the healthy liver, agrin and perlecan are the components of basement membranes of the blood vessels; their increased amounts can be detected not only there but also in the connective tissue of the liver cirrhosis and cancer." (PMID 35186754, 2022). "The importance of agrin was suggested in the early phase of cancer development." (PMID 35186754, 2022). "The landscape map demonstrated Agrin expression levels in 33 types of cancers." (PMID 35111682, 2021). "Recent studies show that Agrin plays important roles in cancers and immune system." (PMID 35111682, 2021). "Agrin was reported to be upregulated in various cancers than the adjacent normal tissues." (PMID 35111682, 2021). "In support of these findings, it was shown that agrin, produced both by the cancer cells, as well as the vascular endothelial cells, is required for activation of angiogenesis, blood vessel sprouting and cancer cell adhesion to the endothelial cells." (PMID 33330449, 2020). "A knock-down of agrin reduced cancer cell proliferation, invasion and sphere formation." (PMID 33330449, 2020). "In recent years, agrin has been revealed to play an important role in cancer development." (PMID 32612983, 2020). "Hence, we are looking forward to an exciting avenue of research aimed at understanding the agrin-YAP pathway in the context of aggressiveness of cancers." (PMID 29415512, 2018). "In addition to cancer models, the role of agrin as a critical regulator of YAP function has been concomitantly discovered in multiple organs." (PMID 29415512, 2018). "Moreover, agrin also provided contractile strength to cancer cells in a YAP dependent manner and conferred significant matrix stiffness to otherwise compliant collagen gels." (PMID 29415512, 2018). "Is this agrin-YAP mechanotransduction network active in chemotherapy-resistant cancer cells, and targeting this loop may re-awaken cancer cell sensitivity to chemotherapy?" (PMID 29415512, 2018). "Agrin conferred contractility to cancer cells that remodeled collagen lattices." (PMID 29415512, 2018). "In addition, as soluble C-terminus fragment of agrin rescued YAP activity in agrin-depleted cancer cells further suggesting that agrin engages its receptors for mediating downstream effects on YAP." (PMID 29415512, 2018).
cancer (continued). "Since secreted neural Agrin aggregates acetylcholine receptors, we next examined whether it is secreted in cancer cell lines and hence can potentially act as a biomarker." (PMID 25630468, 2015). "Since cell surface proteins are the best known therapeutic targets in most cancers, our results suggest that targeting Agrin may be a potential approach to suppress HCC." (PMID 25630468, 2015). "Therefore, we selected the basement membrane related gene AGRN for pan-cancer analysis." (PMID 37841281, 2023). "In addition to cancer cells and cancer-associated fibroblasts, ECM stiffening during tumor progression induces vascular cell growth and allows blood vessel infiltration, potentially through the Agrin-YAP-dependent mechanism." (PMID 34109179, 2021). "Whether agrin acts following a similar pathway also in cardiac angiogenesis is unknown, but since the agrin isoforms produced within growing tumors by cancer cells and ECs have a similar angiogenic effect, it could be speculated that this specific agrin axis could be the same acting in cardiac ECs." (PMID 32612983, 2020). "Moreover, how critical is the agrin-YAP signaling towards altering mechanoresponse of cancer cells?" (PMID 29415512, 2018). "Mechanistically, agrin mechanoactivates EGFR through epidermal growth factor (EGF)‐dependent and independent modes, thereby sensitizing its activity toward localized cancer cell‐ECM adherence and bulk rigidity by fostering interactions with integrin β1." (PMID 40165020, 2025). "Eight proteins (C-reactive protein, AGRN, XPOT, LDHA, C1QC, ORM1, ANGPTL4, and prostaglandin D2 synthase [PTGDS]) exhibited a continuously upward or downward trend in three or more cancer types." (PMID 39884577, 2025). "As an unexpected mechanism, agrin provided ECM‐stiffness cues that activated both wild‐type and mutant EGFR, sustaining its proliferative capabilities in cancer cells." (PMID 40165020, 2025). "Agrin enhances cellular proliferation, migration, and oncogenic signaling by sustaining focal adhesion integrity and regulating extracellular matrix (ECM)–cancer cell communications." (PMID 39123447, 2024). "Differentially expressed PG core proteins between morphological types were agrin, perlecan and collagen alpha-1(VIII) chain, all of which are basement membrane PGs and play an important role in cancer growth and angiogenesis." (PMID 37069213, 2023). "Researchers have also verified the existence of this pathway in PC cells, proving that agrin in cancer stemness extracellular vesicles promotes YAP activation and cancer cell proliferation and inventory." (PMID 37173787, 2023). "More importantly, extensive future research is required to understand the influence of cell mechanics involving agrin and YAP activities in other organs and cancer types." (PMID 29415512, 2018). "In vivo, agrin depletion also reduced the fibrillary collagen content, an indication that it activates YAP for stiffening and crosslinking the ECM during cancer development." (PMID 29415512, 2018). "More importantly, agrin also stiffened the local ECM and provided considerable contractile strength to the cancer cells." (PMID 29415512, 2018). "In fact, robust positive correlation exist between the expression profiles of agrin, YAP/TAZ and several of their targets across different cancer cell lines." (PMID 29415512, 2018). "In conclusion, we reveal Agrin as an important factor activating and coordinating cellular adhesion, migration and invasiveness of HCC cancer cells." (PMID 25630468, 2015). "Agrin and perlecan are two of the major HSPG identified in the basement membrane, and their functional roles in modulation of cancer growth have been reviewed elsewhere." (PMID 25506919, 2014). "In an interesting observation, while employing DepMap, we noted that several cancer cells that were sensitive to osimertinib had a negative score for agrin in addition to phosphorylated EGFR." (PMID 40165020, 2025).
cancer (continued). "We evaluated the concentration of agrin levels in patients diagnosed with hepatobiliary cancer relative to matched controls from our biorepository, who exhibited no signs of cancer." (PMID 39123447, 2024). "Importantly, agrin was shown to be secreted by HCC cells, endothelial and hepatic stellate cells, and to generate oncogenic signaling that enhances cancer cell proliferation, migration, and EMT through a mechanism that is Arp2/3-dependent." (PMID 35454809, 2022). "For example, high expression of pericellular agrin on the interface between the cancer cells and the surrounding ECM, serves as a strong negative prognostic marker in PDAC." (PMID 33330449, 2020). "Whether agrin and YAP/TAZ team up as oncogenic drivers in other cancer(s) will be one interesting area in cancer research." (PMID 29415512, 2018). "Importantly, the growth of localized or metastatic cancer cells was not affected after implantation into endothelial agrin depleted mice." (PMID 35174224, 2021). "It will be certainly worth to investigate this point further, in order to understand whether, irrespective of the ECM receptors involved, agrin employs a similar strategy to stimulate proliferation of CMs and cancer cells." (PMID 32612983, 2020). "Therefore, it is tempting to speculate that agrin may control NMJ and cancer progression through the concerted activities of YAP and β-catenin." (PMID 29415512, 2018). "Essentially, cancer cells displayed fragmented focal adhesions and lack of FAK phosphorylation in response to agrin depletion, an effect that was restored by supplementation of soluble agrin in the matrix." (PMID 29415512, 2018).
neuromuscular disease (5 papers, 2014 to 2022). "Future experiments will reveal if NT-1654 can be of benefit in the treatment of human neuromuscular diseases that directly or indirectly affect the agrin/Lrp4/MuSK pathway." (PMID 24520420, 2014).
neurological disease (4 papers, 2012 to 2017). "Specifically, a loss of the instructive role of laminin or agrin could figure prominently in neurological disease." (PMID 24777283, 2015). "Another gene with cryptic splicing seen in both K562 datasets and in the initial Ling HeLa data, AGRN, was recently shown to be decreased at the protein level in the cerebrospinal fluid of ALS patients compared to healthy controls and other neurological diseases." (PMID 28549443, 2017).
adenocarcinoma (3 papers, 2016 to 2025). A common cancer characterized by the presence of malignant glandular cells. "The clustering also highlighted a set of proteins that was almost solely present in control tissue of adenocarcinoma patients, including FANCJ, CCAR2, AGRIN, and LAMC1." (PMID 26930711, 2016).
Kidney Disease (3 papers, 2015 to 2025). "The uncontrolled regulation of ECM components, such as collagens, proteoglycans, and glycoproteins (e.g. agrin, decorin, versican, biglycan, and laminins), has been described in numerous kidney diseases." (PMID 40524147, 2025).
kidney (2 papers, 2017 to 2025). "Importantly, combination treatments targeting EGFR and YAP/TAZ‐TEAD were effective in restraining lung tumorigenesis by blocking agrin as a central player in this oncogenic module, thereby revealing new vistas to combat EGFR‐driven lung malignancies." (PMID 40165020, 2025).
bacterial infections (1 paper, 2021). "Furthermore, our study would pave the way to investigate whether Agrin levels are decreased in the skin tissues of diabetic patients and those infected with bacterial infections, presenting a basis for chronic delayed healing of wounds in these patients." (PMID 34732729, 2021).
immune diseases (1 paper, 2021). "Based on the reports of Agrin in auto-immune diseases and T cells, we further explored the influence of Agrin on T cells in NSCLC TIME." (PMID 35111682, 2021).
inflammation (1 paper, 2017). Aberrant reaction of the microcirculation characterized by movement of fluid and leukocytes from the blood into extravascular tissues. "Moreover, agrin level of sorafenib-treated rats was significantly lower than the sorafenib-untreated rats, implicating DEN-induced liver inflammation by activated HSC through agrin secretion." (PMID 29285255, 2017).
AGRN also shares sentences with these, for which no sentence is quoted: cholangiocarcinoma (3 papers); acinar adenocarcinomas (1); acute myocardial infarction (1); amyloid (1); arthrogryposis (1); asthma (1); astrocytomas (1); atrial fibrillation (1); brain injury (1); cardiac hypertrophy (1); cataract (1); Cenani-Lenz syndrome (1); cervical cancer (1); channelopathies (1); chronic allograft nephropathy (1); diabetic cardiomyopathy (1); Diffuse mesangial sclerosis (1); Dystonia (1); Emery-Dreifuss muscular dystrophy (1); endothelial dysfunction (1); epidermolysis bullosa (1); glomerulopathies (1); Hepatitis (1); hyperplastic polyp (1); hypertrophic cardiomyopathy (1); infection (1); invasive breast carcinoma (1); invasive carcinoma (1); Leukoaraiosis (1); Leukoencephalopathy (1).
A further 23 diseases each share a sentence with AGRN in 1 paper.